ENSG00000256500 (novel protein)
Gene: Protein-coding gene on chromosome 14 (103,562,962 to 103,685,924, forward strand). Ensembl gene ENSG00000256500.
Genetic constraint (gnomAD): Loss-of-function variants: 32 observed, 75.85 expected, observed/expected ratio (o/e) 0.42, 90% interval 0.32 to 0.57. Missense variants: 600 observed, 823.12 expected, observed/expected ratio (o/e) 0.73, 90% interval 0.68 to 0.78. Synonymous variants: 328 observed, 311.6 expected, observed/expected ratio (o/e) 1.05, 90% interval 0.96 to 1.15.